FGF23 (fibroblast growth factor 23)
Diseases named in the same sentence as FGF23 in open-access papers (continued):
Sharing a sentence is not in itself a finding about the gene and the disease.
chronic kidney disease (continued). "We also identified FGF-23—a protein associated with cardiac hypertrophy, chronic kidney disease, and vascular stiffness—as a robust marker for AF." (PMID 30615112, 2019). "FGF-23 is elevated with decreasing kidney function and is associated with all-cause mortality and cardiovascular disease in patients with chronic kidney disease." (PMID 30615112, 2019). "It is known that FGF23 is increased in different pathologies including chronic kidney disease, heart failure or X-linked hypophosphatemia and directly correlates with negative outcome and mortality in severe diseases." (PMID 32309615, 2019). "FGF23 is increased in different pathologies including chronic kidney disease, heart failure or X-linked hypophosphatemia." (PMID 32309615, 2019). "Elevated levels of FGF23 in individuals with chronic kidney disease (CKD) are associated with adverse health outcomes, such as increased mortality, large vessel disease, and reduced white matter volume, cardiovascular and cerebrovascular events." (PMID 30192823, 2018). "Chronic kidney disease causes disturbances in the mineral balance and concomitant high levels of plasma FGF23 and PTH." (PMID 29063159, 2018). "Both the activation of the renin angiotensin aldosterone system (RAAS) and elevations of circulating Fibroblast Growth Factor-23 (FGF-23) have been implicated in the pathogenesis of left ventricular hypertrophy (LVH) in chronic kidney disease." (PMID 30120363, 2018). "Excess FGF-23 is associated with inflammation and adverse infectious outcomes, as well as increased morbidity and mortality, particularly in patients with chronic kidney disease." (PMID 29946298, 2018). "FGF23 is a 27-kDa protein that has been shown to be strongly associated with the risk of chronic kidney disease progression, systemic inflammation, and mortality." (PMID 30538676, 2018). "Previous studies have reported higher FGF23 levels as a risk factor for death, end-stage renal disease, and CVD2–4." (PMID 30228288, 2018). "Fibroblast growth factor 23 (FGF23) is an independent risk factor for cardiovascular mortality in chronic kidney disease." (PMID 29137111, 2017). "Overall, these studies indicate a vital role of FGF23 in vascular calcification, a process commonly associated with chronic kidney disease (CKD) and coronary artery disease." (PMID 28974056, 2017). "Significantly, elevated intact FGF23 occurs in chronic kidney disease and upon kidney transplant where it is directly linked to poor prognosis due to its effects on renal phosphate reabsorption and 1,25-dihydroxyvitamin D biosynthesis." (PMID 28362263, 2017). "High levels of FGF23, for example, can cause serious and often fatal problems in patients with chronic kidney disease." (PMID 28362263, 2017). "The decrease in FGF23 level, for which elevations seem to be a novel risk factor for end-stage renal disease (ESRD), cardiovascular disease, and mortality, was most pronounced in patients with the highest levels at baseline." (PMID 28505087, 2017). "It has also been shown that myocardial FGF23/FGFR4 expression is associated with cardiac hypertrophy among patients with end-stage renal disease." (PMID 27400031, 2016). "Several studies showed that higher FGF23 levels were associated with the development of artery calcification, particularly in the presence of chronic kidney disease." (PMID 26459301, 2015). "Multivariable-adjusted associations between natural log-transformed fibroblast growth factor-23 and anthropometrics (BMI and WC, waist circumference) in the overall sample and by chronic kidney disease (CKD) status." (PMID 25811862, 2015). "Despite the potential of FGF23 to serve as a HF marker the increase of circulating FGF23 is often associated with faster progression of chronic kidney disease and a higher mortality of hemodialysis patients." (PMID 26236717, 2015).
chronic kidney disease (continued). "Elevated serum phosphorus, calcium, and fibroblast growth factor 23 (FGF23) levels are associated with cardiovascular disease in chronic renal disease." (PMID 26221597, 2015). "High levels of circulating fibroblast growth factor 23 (FGF23) are associated with chronic kidney disease (CKD) progression and high mortality." (PMID 24885942, 2014). "Higher FGF-23 levels were reported to be independently associated with higher levels of inflammatory markers in patients with chronic kidney disease." (PMID 24782595, 2014). "High FGF23 levels were associated with an increased all-cause mortality in hemodialysis patients, increased risk for end stage renal disease (ESRD), cardiovascular events and mortality in CKD patients." (PMID 24991914, 2014). "Plasma FGF23 levels also predict the risk of progression of chronic kidney disease: the higher FGF23 concentrations, the higher risk of decrease in renal function." (PMID 23825530, 2013). "High plasma fibroblast growth factor-23 (FGF23) concentration predicts the risk of death and poor outcomes in patients with chronic kidney disease or chronic heart failure." (PMID 23825530, 2013). "High FGF23 concentration has been associated with elevated mortality in patients with various stages of chronic kidney disease or chronic heart failure or in community even in the absence of alteration of renal function." (PMID 23825530, 2013). "Higher levels of FGF23 were associated with the development of coronary artery calcification, particularly in the presence of chronic kidney disease." (PMID 24015259, 2013). "Elevated levels of FGF23 have been associated with risks of end-stage renal disease, cardiovascular disease and mortality." (PMID 23455471, 2013). "In the Chronic Renal Insufficiency Cohort Study during 3.5 years of follow-up elevated FGF-23 was an independent risk factor for ESRD." (PMID 23526964, 2013). "Recent studies demonstrated that circulating fibroblast growth factor (FGF)-23 was associated with risk of end stage renal disease (ESRD) and mortality." (PMID 23526964, 2013). "Osteoprotegerin (OPG) and fibroblast growth factor-23 (FGF23) are recognized as strong risk factors of vascular calcifications in non dialysis chronic kidney disease (ND-CKD) patients." (PMID 22567137, 2012). "Higher levels of FGF23 are associated with increased mortality in hemodialysis-patients and in patients with chronic kidney disease (CKD) stage 2-4." (PMID 22742720, 2012). "Elevations of circulating Fibroblast growth factor 23 (FGF23) are associated with adverse cardiovascular outcomes and progression of renal failure in chronic kidney disease (CKD)." (PMID 22970174, 2012). "Fibroblast growth factor-23 (FGF-23), a novel regulator of mineral metabolism, is markedly elevated in chronic kidney disease and has been associated with poor long-term outcomes." (PMID 21906363, 2011). "We demonstrated for the first time that FGF-23, a critical regulator of mineral metabolism in chronic kidney disease, is upregulated during acute kidney injury from causes other than rhabdomyolysis." (PMID 21906363, 2011). "We expect that further efforts on modeling and experimental evaluation would contribute to diagnosing patients with metabolic diseases such as osteoporosis and chronic kidney diseases, and developing FGF23-linked treatment strategies." (PMID 19838340, 2009). "Previous evidence showed that the iFGF23 levels are negatively correlated with the BMD in end-stage renal disease patients, suggesting that FGF23 may predict bone loss." (PMID 40142640, 2025). "FGF23 plays a key role in regulating phosphate metabolism and is implicated in conditions such as inherited hypophosphatemia rickets, familial tumoral calcinosis, X-linked hypophosphatemia, and the progression of chronic kidney disease." (PMID 41394119, 2025).
chronic kidney disease (continued). "However, they found that a higher plant protein intake was associated with lower serum levels of FGF-23, a biomarker that reflects chronic kidney disease–mineral and bone disorder, earlier than serum phosphate." (PMID 40871676, 2025). "Elevated levels of FGF23 are associated with faster progression to end-stage renal disease." (PMID 41426862, 2025). "This study aimed to assess whether anemia and/or iron deficiency are associated with increased circulating concentrations of FGF23 in the large, well-characterized Chronic Kidney Disease in Children (CKiD) study cohort." (PMID 37752381, 2024). "Moreover, recent investigations have linked FGF23 to the immune system in chronic kidney disease; FGF23 induces TNF-α expression and macrophages in response to immunological stimuli in mice, suggesting its role in inflammatory processes." (PMID 37108717, 2023). "There is evidence that high levels of FGF23 in patients with chronic kidney disease may increase the risk of death." (PMID 36829583, 2023). "In addition to causing hyperphosphatemia, elevated FGF23 is associated with chronic kidney disease progression and mortality." (PMID 35231062, 2022). "Thus, FGF-23 was positively associated with previous heart failure and previous chronic renal failure." (PMID 36132198, 2022). "Whether the association between aldosterone activation and plasma FGF23 exists beyond kidney stone formers remains to be validated, e.g., in populations of healthy volunteers and of patients with chronic kidney disease or congestive heart failure." (PMID 35201364, 2022). "Moreover, plasma FGF-23 is a risk factor for MACCE in patients with end-stage renal disease (ESRD) receiving continuous ambulatory peritoneal dialysis (CAPD)." (PMID 36132198, 2022). "In addition, clinical evidence regarding the effects of FGF23 on bone mass and fragility fractures suggest potential diagnostic and prognostic applications of FGF23 in clinical contexts, particularly in elderly and patients with chronic kidney disease." (PMID 35269640, 2022). "Furthermore, increased serum FGF23 concentrations are associated with chronic kidney disease, which is the most common cause of death in aging cats." (PMID 36428422, 2022). "Numerous clinical studies have indicated that elevated FGF23 (fibroblast growth factor 23) levels may be associated with cardiovascular (CV) mortality, especially in patients with chronic kidney disease." (PMID 35736431, 2022). "Chronic kidney disease is among others characterized by a disturbed FGF23-associated mineral metabolism and studies support the concept that concomitant hyperphosphatemia may promote FGF23’s cardiac toxicity." (PMID 34778257, 2021). "Multiple studies have shown that FGF23 level increases in the very early stages of chronic kidney disease (CKD), and its concentration may also be highly associated with cardiac complications." (PMID 34055103, 2021). "Results of the Chronic Renal Insufficiency Cohort (CRIC) showed that higher FGF23 levels are associated with higher levels of the inflammatory markers CRP, IL6, TNFα, and fibrinogen and with a higher odds ratio for severe inflammation independent of mineral metabolism and renal function." (PMID 34208131, 2021). "Fibroblast growth factor-23 (FGF23) appears to be one of the most promising biomarkers and predictors of cardiovascular risk in patients with heart disease and normal kidney function, but moreover in those with chronic kidney disease (CKD)." (PMID 34065339, 2021). "Iron‐deficiency anemia is a potent stimulator of the phosphaturic hormone FGF23, and anemia, elevated FGF23, and serum phosphate are all significant risk factors for chronic kidney disease (CKD) patient death; however, the contribution of anemia to circulating FGF23 in CKD is not understood." (PMID 32476270, 2020).
chronic kidney disease (continued). "Much interest has been paid to “off-target” effects of FGF23 in other metabolic bone disorders, such as X-linked hypophosphatemia and chronic renal insufficiency, where excess FGF23 has been associated with varying effects on the cardiovascular, gastrointestinal, immune, and central nervous systems." (PMID 32457699, 2020). "Chronic kidney disease is the main cause of a secondary increase in FGF23 level." (PMID 30909513, 2019). "However, an intriguing finding was that FGF-23 neutralization, although improving chronic kidney disease-associated hyperparathyroidism, increased mortality in a rat model of chronic kidney disease." (PMID 31791247, 2019). "Therefore, it has been postulated that massive elevations in circulating levels of FGF23, as found in patients with chronic kidney disease, contribute to associated pathologies by targeting cells and tissues that lack klotho." (PMID 29770125, 2018). "The association between low vitamin D and high FGF-23 serum levels with infectious and cardiac deaths in a large cohort of patients with end-stage renal disease may be due to the loss of the anti-inflammatory effects of 1,25D." (PMID 29946298, 2018). "FGF23 has been characterized as a hormonal regulator of circulating phosphate and vitamin D levels as well as a prognostic risk factor for cardiovascular mortality in patients with chronic kidney disease." (PMID 30538676, 2018). "In addition, serum FGF23 concentration has been associated with the progression of chronic kidney disease." (PMID 29949887, 2018). "In addition, FGF23 serum levels are identified as an independent risk factor for end-stage renal disease and cardiovascular mortality in CKD patients." (PMID 29073196, 2017). "A more complete understanding of these aspects of osteocyte biology may help to design novel treatments for the mineralization defects observed in diseases associated with excessive osteocytic Fgf23 secretion such as XLH or chronic kidney disease." (PMID 27035636, 2016). "Elevated levels of FGF23 were described primarily in the context of impaired renal function and as being associated with worse clinical outcomes in patients with cardiac and/or chronic kidney disease." (PMID 25902817, 2015). "Similarly, a study carried out in patients with advanced chronic kidney disease showed that low plasma vitamin D levels were associated with death and initiation of long-term dialysis, but FGF-23 levels attenuated this relationship." (PMID 24748388, 2014). "Our findings suggest that FGF23 is a key regulator of renal Na+ reabsorption and plasma volume, and may explain the association of FGF23 with cardiovascular risk in chronic kidney disease patients." (PMID 24797667, 2014). "In addition, tissue specific modulation of FGFR1 can conceivably counteract conditions associated with FGF23 resistance or chronic hyperphosphatemia, such as those seen in patients with chronic kidney disease." (PMID 23451204, 2013). "Recent observational data suggest that FGF23 is associated with and may represent an independent risk factor for cardiovascular and all-cause mortality in patients with chronic kidney diseases stage of 4 and 5 (eGFR < 30 mL/min)." (PMID 22121479, 2012). "Elevated FGF23 is a hallmark of chronic kidney disease (CKD), but also rises acutely in acute kidney injury (AKI) and appears disproportionately high in autosomal dominant polycystic kidney disease (ADPKD), underscoring condition-specific regulation." (PMID 41783140, 2026). "The intimate relationship between Pi metabolism and PiT/FGF/FGFR signalling may have broader implications for diseases with altered systemic Pi levels such as chronic kidney disease and x-linked hypophosphatemic rickets that are characterised by increased FGF23 serum levels." (PMID 40791815, 2025).
chronic kidney disease (continued). "Whereas higher αKlotho abundance has been shown to provide health benefits to several organs and confer longevity, higher FGF23 plasma levels are associated with chronic kidney disease (CKD) and further cardiovascular disorders, predicting worse outcomes." (PMID 40483378, 2025). "Like FGF-23, it is also produced by osteocytes and has been associated with chronic kidney disease–mineral bone disorder (CKD-MBD)." (PMID 40564142, 2025). "In chronic kidney disease (CKD) patients, FGF23 is involved in CKD-related mineral and bone disorder (CKD-MBD) and has been suggested to be a cardiovascular risk factor." (PMID 38186870, 2024). "Fibroblast growth factor 23 (FGF23) is an important hormone implicated in the pathogenesis of chronic kidney disease-mineral bone disorder (CKD-MBD)." (PMID 37752381, 2024). "An association between increasing FGF-23 levels and progression of chronic kidney disease (CKD) was documented in cats, dogs, and humans." (PMID 38891718, 2024). "Furthermore, increased serum levels of FGF23 are associated with a greater risk of left ventricular hypertrophy, heart failure, and atrial fibrillation and are also independently associated with increased mortality in chronic kidney disease (CKD)." (PMID 38530370, 2024). "In fact, in individuals with chronic kidney disease (CKD), FGF23 is associated with endothelial dysfunction, arterial wall calcification, left ventricular hypertrophy, coronary artery disease and cardiovascular mortality." (PMID 37061530, 2023). "Elevated serum FGF23 is a known independent risk factor for mortality in chronic kidney disease (CKD) patients." (PMID 36829583, 2023). "Excess FGF23 also correlates with chronic kidney disease (CKD) and acute kidney injury, where it is associated with increased morbidity and mortality." (PMID 37681408, 2023). "Neutralizing inflammatory cytokines (TNF) can reduce the level of FGF23 in animal models of chronic kidney disease (CKD) and high levels of FGF23 are associated with increased cardiovascular morbidity and mortality in patients with CKD." (PMID 35370667, 2022). "Fibroblast growth factor 23(FGF23) is the most important biomarker and pathogenic factor in Chronic Kidney Disease–Mineral and Bone Disorder (CKD–MBD)." (PMID 35801203, 2022). "Fibroblast growth factor (FGF)‐23 is increased first in the sequence of changes associated with chronic kidney disease (CKD)‐mineral and bone disorder." (PMID 34418162, 2021). "One of the best-studied pathologies associated with overactivated FGF23 signaling is chronic kidney disease (CKD), the latter being defined by persistent (>3 months) kidney dysfunction (GFR <60 mL·min−1 per 1.73 m2)." (PMID 34050126, 2021). "In the early stages of chronic kidney disease (CKD), an increase in fibroblast growth factor-23 (FGF23) and parathyroid hormone (PTH) cause a reduction in the tubular resorption of phosphate (P)." (PMID 33498560, 2021). "Fibroblast growth factor 23 (FGF23) is a key phosphate-regulating hormone that has been associated with adverse outcomes in patients with chronic kidney disease (CKD)." (PMID 32857288, 2020). "Nowadays FGF23 has gained wide attention in chronic kidney disease associated mineral bone disease (CKD-MBD) and appears to be a candidate as missing link between chronic kidney disease and cardiovascular morbidity and mortality." (PMID 32130720, 2020). "The over-expression of FGF23 has also been associated with various aspects of cardiovascular disease in chronic kidney disease (CKD) including cardiomyocyte hypertrophy, vascular calcification, stroke, and endothelial dysfunction." (PMID 30808384, 2019). "Thus, end-stage renal disease is an α-klotho deficiency state characterized by clinical and laboratory abnormalities that include high levels of FGF23, presence of hyperphosphatemia, vascular calcification, LVH, bone disease, premature aging, and high mortality." (PMID 30087898, 2018).